APC (APC regulator of Wnt signaling pathway)
Diseases named in the same sentence as APC in open-access papers (continued):
Sharing a sentence is not in itself a finding about the gene and the disease.
tumor (continued). "Characterisation of kinesin-1 as a novel binding partner of APC has implications for the tumour suppressor activity of APC, since the interaction occurs through the C-terminal region that is lost after tumourigenic truncating mutations." (PMID 27272132, 2016). "Regarding APC an intense nuclear staining was noted in 53% of the cases and this staining pattern was a significant predictive factor for tumor recurrences, both overall and at distant sites." (PMID 27577083, 2016). "As a tumor suppressor, APC protects β-catenin from dephosphorylation and enhances β-catenin degradation." (PMID 27769064, 2016). "In evaluating AZ1366 single agent efficacy in our CRC PDTX models, we identified a significant reduction in tumor growth in 6 (2 APC wild type and 4 APC mutant) out of 18 unique models." (PMID 27070088, 2016). "Firstly, the APC I1307K germline mutation is associated with increased risk for CRC development, tumor location, and tumor stage." (PMID 27595705, 2016). "Since we analyzed FFPE samples, we sequenced exclusively the small part of the APC gene corresponding to the Mutated Cluster Region (MCR) and we found the missense mutation GAA>AAA E1544K in one tumor (10% of cases)." (PMID 27062580, 2016). "While tumours with two different APC mutations may fit the bi-allelic theory, tumours with one mutation are of particular interest because they have improved overall survival and statistically significant different biological profiles from both APCwt and two-hit APC tumours." (PMID 27302369, 2016). "This is particularly relevant in gastrointestinal tumors, as proven in a mouse model of colon cancer (transgenic APC+/min strain), where gut barrier was disrupted along with tumor growth, resulting in increased systemic inflammation and endotoxemia." (PMID 26900952, 2016). "The Fzd7 extracellular domain has also been shown to potently inhibit the growth of APC mutant CRC tumour cells in a mouse xenograft model." (PMID 27196929, 2016). "Loss of APC leads to a constant activation of WNT signaling, which promotes proliferation of tumor cells." (PMID 27092172, 2016). "It is well known that both APC and CTNNB1 mutation are frequently happened in CRCs and are critical for carcinogenesis and progression of CRCs, including tumor initiation and metastasis." (PMID 27880730, 2016). "Most of APC/C regulated cellular functions are directly or indirectly connected to tumor initiation or invasion." (PMID 27418942, 2016). "However, the role of the suppression of APC and the activation of the canonical Wnt signaling in the tumor initiation process of the tissues other than the colon largely remain unknown, because APC mutations are less frequent in tumors originating from these tissues." (PMID 26712794, 2015). "Similar to adenomatous polyposis coli (APC) – a tumour suppressor that links MTs to actin, Kar9 mediates interactions of aMTs with cortical actin that are required for pre-anaphase spindle positioning and nuclear migration close to the bud." (PMID 26395399, 2015).
tumor (continued). "The tumour suppressor APC is highly concentrated at the tips of the processes and in the somas of RGCs and is required for the maintenance and extension of the radial glial processes." (PMID 26382033, 2015). "For example, miR-129-5p has an oncogenic role in LSCC and directly inhibits the tumour suppressor APC." (PMID 26286725, 2015). "Knockdown of miR-142 upregulates the APC expression, reduces the clonogenicity of human breast CSCs in vitro, and suppresses the tumor growth initiated by the human breast CSCs in vivo." (PMID 26712794, 2015). "The methylation rates of APC or RASSF1A in the plasma of tumor-bearing nude mice were highest at 24 h after injection." (PMID 26550041, 2015). "Because of its essential roles in chromosome segregation and mitotic progression, the APC/C has become a therapeutic target for the treatment of multiple neoplastic diseases." (PMID 24948786, 2014). "Hypermethylation of APC, a well-characterized tumor suppressor, has been detected frequently in HCC in various studies." (PMID 24765201, 2014). "The APC tumor suppressor gene illustrates a provocative example in which a single, population-specific, germline SNP can affect disease risk by altering the mutagenic potential of a microsatellite sequence." (PMID 25033203, 2014). "Another study investigated the correlation between APC hypermethylation in PC tumor tissue and BCR using qMSP analysis of 219 RP specimens." (PMID 25238417, 2014). "All 3 tumor samples had KRAS mutations, while 2 tumors contained mutations in the APC gene and the PIK3CA gene." (PMID 24943349, 2014). "Of the 8 tumors with a size of >4 cm, the mean methylation level of the tumor suppressor gene APC promoter was 13.06%, while for the remaining 49 patients with a smaller tumor, the mean methylation level was 2.96%." (PMID 24765201, 2014). "Adenomatous polyposis coli (APC) has been reported to be a candidate tumor suppressor in many cancers." (PMID 24661338, 2014). "PTEN and APC, common to two identified gene sets, are tumor suppressors that are known to interact in cancer." (PMID 24675718, 2014). "In multivariate analysis, APC hypermethylation was a significant predictor of BCR only in the subgroup consisting of 141 patients with tumor stage pT2 (HR (95% CI): 2.174 (1.044–4.530), p = 0.038)." (PMID 25238417, 2014). "Our findings identify mutant APC as a potential tumor biomarker of resistance to 5-FU, and importantly we show that APC-mutant CRC cells can be made more sensitive to 5-FU by use of Chk1 inhibitors." (PMID 25301724, 2014). "In an intestinal adenoma model where APC is deleted in LGR5+ intestinal stem cells, mice deficient in TIGAR showed a reduction in total tumor burden and average tumor size in the small intestine compared to wild-type mice." (PMID 24383451, 2014). "APC is a tumor-suppressor gene and an essential component of the beta-catenin complex which controls cytoplasmic beta-catenin levels." (PMID 24931005, 2014). "The APC locus is another example that a simultaneous visualization of deletion and mutation tracks in FISH Oracle 2 supports detection of "typical" tumor suppressor genes following the "second hit" sequence of inactivation." (PMID 24684958, 2014). "Eighteen of the 23 patients had at least one tumour with an identified molecular change other than APC LOH or c.3924_3925insA in the region studied." (PMID 24416237, 2014).
tumor (continued). "APC functions as an intracellular regulator of Wnt/β-catenin signal transduction, which is thought to represent its main tumor suppressing activity." (PMID 24678719, 2014). "However, the role of the suppression of APC and the activation of the canonical WNT signaling in the tumor initiation process of the tissues other than the colon largely remains unknown, because APC mutations are less frequent in tumors originating from these tissues." (PMID 25406066, 2014). "Our findings confirm that genetic alterations that occur early in colorectal carcinogenesis, namely mutations in APC, KRAS, NRAS, and BRAF, persist through tumor evolution and show an exceedingly high level of concordance between primary tumor and metastases." (PMID 25164765, 2014). "Summary of pattern of mutations among the 75 tumours informative for presence of the c.3924_3925insA somatic mutation, loss of Heterozygosity (LOH) at APC and number of nonsense or frameshift mutations." (PMID 24416237, 2014). "APC is a key tumor suppressor that regulates the canonical WNT signaling pathway and is involved in development and homeostasis of a variety of cells including stem cells." (PMID 25406066, 2014). "We found variants in the five genes APC, BRCA1, RET, RNASEL, and STK11 that were linked to autosomal dominant forms of cancer or neoplasm as well as four complex risk variants in ELAC2, MSR1, AIP, and SDHB." (PMID 25333069, 2014). "The authors show negative association between serum 25-D3 level and CGI methylation of the adenomatous polyposis coli (APC) promoter region, a tumor suppressor often inactive in colorectal cancer." (PMID 24808866, 2014). "The analysis of tumours from FAP patients has revealed that cancer cells always retain a truncated APC which very rarely lacks the first 15R (2 cases out of 328 tumours)." (PMID 23840886, 2013). "Together, these data suggest that miR-129-5p has an oncogenic role in LSCC and that it directly inhibits the tumour suppressor APC and allows increased Wnt signalling to occur." (PMID 24194897, 2013). "As a tumour suppressor, APC controls β-catenin function in transcription 37 and thus blocks the nuclear translocation of β-catenin." (PMID 24015932, 2013). "In consideration of negative regulation of miRNA, we notice APC, a tumour suppressor, among these potential targets for miR-129-5p." (PMID 24194897, 2013). "Our study demonstrates that the localization of APC/β-catenin-rich complexes at membrane protrusion ends is required for tumor cell morphology and motility." (PMID 23302090, 2013). "APC is generally considered a key component of the Wnt signaling pathway, and its primary function as tumor suppressor is believed to be its ability to negatively regulate the Wnt pathway." (PMID 23405266, 2013). "An initial concern was that due to the striking morphological and growth similarities between FEnS and APC null adult organoids, transplantation of FEnS in vivo would lead to tumor formation." (PMID 24139758, 2013).
tumor (continued). "APC is a well-known tumor suppressor, which plays a central role in the Wnt signaling pathway by targeting β-catenin for degradation." (PMID 23738079, 2013). "This shuttling plays an important role in APC’s tumor suppressor function because it serves to promote nuclear export of ß-catenin." (PMID 23520519, 2013). "We chose the APC+/1638N mutant mice, which were shown to develop tumours in the intestinal tract at a moderate level." (PMID 23940460, 2013). "However, our findings support the concept that the timing of APC loss during tumor progression may be important in dictating the biological consequences and suggest that APC, and its downstream effectors, might even represent novel therapeutic targets to modulate tumor metastasis." (PMID 23302090, 2013). "Deming and colleagues demonstrated that the simultaneous presence of APC and PI3KCA gene mutations in animal models are associated with increased tumor multiplicity and size, and a more aggressive behavior." (PMID 23965959, 2013). "This is likely to be the case because mutant APC appears to have a gain-of-function binding to the Asef proteins that control tumor cell migration." (PMID 23302090, 2013). "Our results suggest that the tumor attenuation previously observed in APC+/min mice carrying a systemic deletion of SIRT1 was a tissue-specific effect of SIRT1-deficiency." (PMID 23799088, 2013). "APC, a tumor suppressor, is a negative regulator of the β-catenin oncoprotein, and mutations in APC lead to elevated levels of β-catenin in the cytoplasm, which in turn induce changes in proliferation, differentiation, migration, adhesion, and apoptosis." (PMID 23785264, 2013). "Unfortunately, we were unable to separate a contribution of APC specifically to tumor cell invasion from its impact on motility (M.O and K.H.G., unpublished observations)." (PMID 23302090, 2013). "Our results indicate that SIRT1 acts as a tumor promoter in the APC+/min mouse model of intestinal tumorigenesis." (PMID 23799088, 2013). "The study revealed that APC, the best-known tumor suppressor of human CRC, was the most recurrently deleted gene in both canine adenomas and adenocarcinomas." (PMID 23251390, 2012). "Second, at tumor suppressor genes mean methylation level was higher in patients than in controls, with the exception of APC SN2." (PMID 22629410, 2012). "For example, partial hepatectomy promotes tumour formation, APC is a tumour suppressor, and PGE2 is known to contribute to tumour promotion." (PMID 22919490, 2012). "Truncated APC is almost always retained in tumour cells, suggesting that it serves an essential function." (PMID 22509309, 2012). "Or in the case of the APC tumour suppressor where binding of CRM1 exportin and active–Ran allow movement of the helix containing the NES within the coiled coil moiety that then unmasks the NES." (PMID 22723967, 2012). "Tumor growth is also inhibited through the interference with the APC/β-catenin and COX-2/PGE2 signaling pathways, which are pivotal in colon carcinogenesis." (PMID 22848209, 2012). "Down-regulation of truncated APC results in an inhibition of tumour cell population expansion in vitro in 6 cell lines out of 6 and inhibition of tumour outgrowth in vivo as analysed in one of these cell lines, HT29." (PMID 22509309, 2012). "The adenomatous polyposis coli (APC) gene is also a tumor suppressor, and its mRNA level is at least partially regulated by DNA methylation." (PMID 23060864, 2012). "By analyzing tumor DNAs from three affected individuals of the same family, they found that APC tumor suppressor gene was somatically inactivated due to the frequent occurrence of G:C to T:A transversions." (PMID 22876359, 2012).
tumor (continued). "The tumour suppressor Adenomatous Polyposis Coli (APC) is required for proper mitosis; however, the exact role of APC in mitosis is not understood." (PMID 22719865, 2012). "In conclusion, the present study showed aberrant tumor-specific methylation alterations for APC, BIN1, BMP6, BRCA1, CST6, ESR-b, GSTP1, P14, P16, P21, PTEN and TIMP3 in the studied cohort." (PMID 22695536, 2012). "The main APC's tumour suppressing function resides in its capacity to regulate the Wnt signal transduction pathway." (PMID 21931686, 2011). "Adenomatous polyposis coli (APC) is a key tumor suppressor gene that acts as a gatekeeper of intestinal epithelial homeostasis by restraining cytoplasmic cellular levels of β-catenin, the central activator of transcription in the Wnt signaling pathway." (PMID 21859464, 2011). "APC (adenomatous polyposis coli) is a multifunctional tumor suppressor that is involved in the initiation and progression of colorectal cancer via regulation of the WNT signaling cascade." (PMID 21713073, 2011). "APC is a tumour suppressor known to activate CTNNB1 and wnt pathway signalling, amongst other effects." (PMID 21781349, 2011). "Investigation of protein complexes that link actin, microtubules and APC is likely to reveal important elements of tumor formation." (PMID 21311754, 2011). "Hierarchical clustering showed significant hypermethylation patterns for serum and tumor tissue compared with normal tissue for seven genes (APC, BIN1, BMP6, BRCA1, CST6, P16 and TIMP3)." (PMID 21283676, 2011). "In our study group, 4.0% of the patients displayed methylation of BRCA1 and APC in both tumor and the corresponding PB DNA." (PMID 22129206, 2011). "Regarding the samples from Taiwan, methylation of SFRP1, IRF8, APC and RASSF1A were significantly associated with increased tumor grade, stage." (PMID 21599969, 2011). "Methylation of SFRP1, IRF8, APC and RASSF1A were significantly associated with increased tumor grade and stage in samples from Taiwan." (PMID 21599969, 2011). "MMR deficiency, irrespective of its genetic or epigenetic origin, leads to the mutator phenotype, and FS APC mutations, predominantly in mononucleotide tracks, are more frequent in MSI tumours." (PMID 21901162, 2011). "Among those genes associated with predispositions for colorectal cancer are adenomatous polyposis coli (APC), a tumor suppressor involving cell adhesion, signal transduction and transcription activation, and DNA mismatch repair (MMR) genes." (PMID 21232124, 2011). "The adenomatous polyposis coli (APC) gene is a well-known tumor suppressor that plays a central role in the Wnt signaling pathway by targeting β-catenin for degradation." (PMID 24212796, 2011). "Two of the examined genes, BRCA1 and APC, showed methylation in both tumor and paired PB DNA at frequencies of 4.4% and 4.1%, respectively with one of the paired samples showing methylation of both APC and BRCA1 in tumor and PB DNA." (PMID 22129206, 2011). "In keeping with previous observation, our study also demonstrated that methylation of several genes such as APC and RASSF1A were associated with tumor progression." (PMID 21599969, 2011). "The tumor suppressor APC normally functions to inhibit Wnt/ß-catenin signaling, and APC mutations are oncogenic in tissues such as the colorectal epithelium." (PMID 22136118, 2011). "Understanding the link between APC and the actin cytoskeleton would be a major step forward in understanding the biology of APC and its tumor suppressor activity." (PMID 21311754, 2011).